PIEZO1 (piezo type mechanosensitive ion channel component 1 (Er blood group))
Diseases named in the same sentence as PIEZO1 in open-access papers (continued):
Sharing a sentence is not in itself a finding about the gene and the disease.
bacterial infection (12 papers, 2018 to 2025). "This bacterial infection caused a significant upregulation of Piezo1 channels in the prefrontal (21 ± 3%) and frontoparietal (23 ± 3%) cortices of 12-month old iTG rats, but not the audiovisual cortex (16 ± 2%)." (PMID 30405400, 2018). "They reported that the knockdown of Piezo1 in myeloid cells showed diminished lung inflammation in the presence of bacterial infection in mice." (PMID 35906615, 2022). "The TLR4 receptor and Piezo1 protein form a complex between macrophages, which are stimulated by bacterial infection or LPS, and the Ca2+ influx generated by the activation of Piezo1." (PMID 36615408, 2022). "Upon conditional deletion of PIEZO1 in myeloid cells in the context of P. aeruginosa infection in the lung, the PIEZO1-mediated mechanosensation protected against bacterial infection." (PMID 34322118, 2021). "Here the authors implicate mechanical sensor Piezo1 in the TLR4 mediated host response to bacterial infection and implicate it in the enhancement of macrophage mediated host response." (PMID 34112781, 2021). "In addition to its regulatory role in macrophages, Piezo1 also responds to mechanical cues such as membrane ruffling induced by bacterial infection, highlighting its broader involvement in immune responses." (PMID 40821847, 2025). "Recent study demonstrated that bacterial infection could trigger assembly of the complex of mechanical sensor Piezo1 and Toll‐like receptor‐4 (TLR4), and then augment phagocytosis, mitochondrion‐phagosomal ROS production in macrophage." (PMID 38973085, 2024). "Also, Piezo1 expressed in myeloid cells acts as a sensor of cyclical pressure to resist the invading bacterial infection." (PMID 35906615, 2022). "Taken together, these results suggested that Piezo1 might coordinate TLRs signalling in response to bacterial infection." (PMID 34112781, 2021). "Bacterial infection or LPS stimulation triggers assembly of the complex of Piezo1 and TLR4 to remodel F-actin organization and augment phagocytosis, mitochondrion-phagosomal ROS production and bacterial clearance and genetic deficiency of Piezo1 results in abrogation of these responses." (PMID 34112781, 2021). "Bacterial infection or LPS stimulation promotes the assembly of TLR4 and Piezo1, thus enhancing the calcium influx, which is dependent on Piezo1 and the activation of CaMK II." (PMID 37941053, 2023). "It is important to mention that the Piezo1-positive structures, which formed upon bacterial infection, were also not clearly co-localizing with stained bacteria." (PMID 41236642, 2025). "The main goal of this study was to investigate, whether P. aeruginosa LecB is able to modulate Piezo1 SAC activity at the plasma membrane and/or localization, which could have a drastic impact on host cell processes and help bacterial infection." (PMID 41236642, 2025). "Our data were consistent with those in the previous report where mice lacking Piezo1 exhibited a decreased pulmonary inflammation response in the context of fibrotic autoinflammation or bacterial infection." (PMID 38303078, 2024). "(2018) showed that in TRPM7‐deficient mice and RAW 264.7 cells, lipopolysaccharide (LPS), or bacterial infection promotes reloading of the Piezo1‐toll‐like receptor 4 (TLR4) complex to remodel F‐actin and promote phagocytosis by macrophages, whereas knockdown of Piezo1 inhibits these responses." (PMID 37366640, 2023). "Similarly, upon LPS stimulation or bacterial infection, the induction of mROS and cellular ROS was completely absent in BMDMs cultured on 5 kPa soft matrix regardless of Piezo1 presenting." (PMID 34112781, 2021).
neurodegenerative disease (12 papers, 2021 to 2025). A disorder of the central nervous system characterized by gradual and progressive loss of neural tissue and neurologic function. "The potential abnormal Piezo1 and other MSCs in the neurovascular unit would be a risk factor for the damage of neurovascular coupling in neurodegenerative diseases, and the abnormal cerebral blood flow might attenuate the clearance of Aβ, tau, or α‐syn as well." (PMID 38923822, 2024). "For example, the misfolded protein deposits in neurodegenerative diseases are much stiffer than brain tissue, which upregulates the expression and activation of Piezo1." (PMID 38923822, 2024). "Clinically, drugs targeting Piezo1, such as Piezo1 agonists (e.g., Yoda1), can be used to reduce neuroinflammation, thereby protecting neurons from neurodegenerative diseases." (PMID 39539343, 2024). "Animal studies have shown that Piezo1 antagonists can effectively inhibit inflammation, protect neurons, and suggest its potential clinical application value in neuroprotection and delaying the progression of neurodegenerative diseases." (PMID 41195420, 2025). "Despite these limitations, our study showed that, as in several adult neurodegenerative disease, PIEZO1 DNAm alteration may serve as a potential epigenetic marker associated with early brain dysfunction, such as that observed in infants with NDs." (PMID 40823415, 2025). "Although the role of up/downregulation of Piezo1 in neurodegenerative diseases still has to be fully elucidated, data suggest that this channel could be a new important therapeutic target for AD and other neurodegenerative diseases." (PMID 36231055, 2022). "New findings in the role of mechanosensing channels such as Piezo1 and the Hippo pathway opened the road for the investigation of mechanobiology alteration in peripheral tissues that could help clarify pathological events happening in neurodegenerative diseases." (PMID 36231055, 2022).
neurological diseases (10 papers, 2023 to 2026). "In that, the expression of Piezo1 increases significantly with age, which is likely associated with aging-related neurological diseases." (PMID 39539343, 2024). "Consequently, the study of small-molecule drugs able to inhibit Piezo1 may pave the way for a potential pharmacological intervention to treat neurocognitive deficits or other neurological diseases associated with Piezo1 overexpression." (PMID 36173070, 2023). "Thus, in the present work, we aim to comment on recent developments in studies on the role of Piezo1 in neurological disease-associated processes and consequently, to assess the possibility of targeting this protein in the therapy of various neurological diseases." (PMID 36173070, 2023). "Emerging evidence supports that wide‐distributed, high‐expressed MSCs like Piezo1 play important roles in several neurophysiological processes and neurological disorders." (PMID 38923822, 2024). "In the following years, the role of Piezo1 was shown in several tissues and processes including neurological diseases and inflammation." (PMID 36173070, 2023). "The critical value of PIEZO1 as a mechanosensor expressed in the membranes of the CNS is of growing interest, with an increasing number of studies aiming to discuss its role in neurological diseases." (PMID 36765838, 2023). "Piezo1 seems to be a promising target for multiple neurological diseases, especially due to the existence of its modulators (Jedi1, Yoda1, GsMTx-4)." (PMID 37296586, 2023). "Existing literature suggests that Piezo1 induces autophagy in certain neurological diseases." (PMID 41507149, 2026). "Piezo1, as a mechanosensitive ion channel, not only plays an crucials role in the cardiovascular system but has also gained increasing attention in the occurrence and progression of neurological diseases." (PMID 41195420, 2025). "Our findings demonstrate a crucial relationship between mechanical cues, Piezo1 activation, and NSC survival, offering new insights for enhancing cell‐based therapies for SCI and other neurological disorders." (PMID 41178492, 2026).
genetic diseases (8 papers, 2018 to 2025). "More importantly, various genetic diseases caused by alteration of channel properties are associated with mutations in human PIEZO1 and PIEZO2 genes." (PMID 30745454, 2019). "Thirdly, the treatment of human genetic diseases caused by Piezo1 gene mutations." (PMID 38690080, 2024). "Xerocytosis is a human genetic disease that has been associated with missense mutations in PIEZO1." (PMID 29545531, 2018). "Variable phenotypes are common in genetic disease, and we still have too few cases in this large protein, PIEZO1, to make suitable observations." (PMID 40792030, 2025). "This suggests that cAMP analogs could be particularly beneficial in conditions where mechanotransduction is dysfunctional or impaired, such as in certain forms of vascular disease or genetic disorders affecting Piezo1 signaling." (PMID 40255319, 2025). "Therefore, Piezo1 agonists and inhibitors are being investigated as potential therapeutics for a wide spectrum of human disorders, including acquired and genetic diseases." (PMID 41017814, 2025). "Furthermore, mutations in human PIEZO1 and PIEZO2 genes have been linked to various genetic diseases due to alterations in channel properties." (PMID 30745454, 2019).
inflammation (6 papers, 2023 to 2025). Aberrant reaction of the microcirculation characterized by movement of fluid and leukocytes from the blood into extravascular tissues. "In addition, Piezo1 expressed on endothelial cells is associated with the development of vascular inflammation, which is exacerbated by the overopening of the Piezo1 channel and an inflammatory cascade activated by mechanical signals in the cells." (PMID 39425532, 2024). "We elucidated the mechanotransduction role of Piezo1 in OSS‐mediated endothelial inflammation, identifying the Piezo1‐Ca2+/CaM/CaMKII‐FAK/Src‐YAP axis as a novel signaling cascade." (PMID 39450718, 2024). "Our evidence supported the critical role of Piezo1 in OSS‐induced atherosclerotic endothelial inflammation." (PMID 39450718, 2024). "Piezo1 responds to lung mechanical stress and is involved in the development of lung inflammation by multiple mechanisms." (PMID 37334369, 2023). "Based on the important roles Piezo1 plays in lung inflammation, Piezo1 is expected to be a potential therapeutic target for pulmonary inflammation." (PMID 37334369, 2023). "Combined with the correlation analysis that PIEZO1 expression was positively correlated with inflammatory mediators, IL-1β, TNF-α, and IL-6, it is speculated that PIEZO1 might play a vital role in the development of pulpal inflammation." (PMID 38627713, 2024). "Our study highlights the key role of Piezo1 in atherosclerotic endothelial inflammation, proposing the Piezo1–Ca2+/CaM/CaMKII‐FAK/Src‐YAP axis as a previously unknown endothelial mechanotransduction pathway." (PMID 39450718, 2024).
metabolic disorders (5 papers, 2022 to 2025). "However, under pathological conditions like OA, dysfunction of Piezo1 may lead to metabolic disorders in chondrocytes, accelerating cartilage degradation and joint dysfunction." (PMID 41195420, 2025).
cardiac disease (4 papers, 2021 to 2025). "The therapeutic strategy of using medical devices to modulate PIEZO1 levels presents promising prospects for clinical translation, suggesting a pathway for pioneering treatments in cardiac diseases." (PMID 40344385, 2025). "Despite several studies being carried out on a functional role for Piezo1 in cardiomyocytes and its dysfunctional role in related heart diseases, less is known about its role in cardiac fibroblasts." (PMID 35897650, 2022). "These achievements forced us to look for possible Piezo1 implications also in cardiac diseases, and especially in cardiac fibrosis, highlighting possible new strategies for preserving cardiac health." (PMID 35897650, 2022). "In this context, Piezo1 could be an attractive target to slow or limit the vicious circle in which fibrosis begets fibrosis in cardiac disease." (PMID 33809739, 2021). "Thus, blocking Piezo1 by disrupting the positive feedback loop during pathogenesis might represent a therapeutic strategy for treating human heart diseases." (PMID 33558521, 2021). "Thus, Piezo1 serves as a key cardiac mechanotransducer for initiating mechano-chemo transduction and consequently maintaining normal heart function, and might represent a novel therapeutic target for treating human heart diseases." (PMID 33558521, 2021).
blood disorder (2 papers, 2020 to 2025). "Piezo1/2 are also the first type of MS channels documented to underlie a human disease linked to mechanical pathologies including a number of blood disorders and problems with proprioception." (PMID 32186512, 2020). "We herein present a case of DHS diagnosed in a 60-year-old female patient with no previously known history of a blood disorder; numerous stomatocytes were seen on peripheral smear, with next-generation sequencing (NGS) revealing a heterozygous PIEZO1 gene mutation." (PMID 40937223, 2025).
brain diseases (2 papers, 2023). "While considering the role of Piezo1 in brain diseases associated with brain vasculature, it should also be emphasized that its significance was examined in the context of brain ischemia." (PMID 36173070, 2023). "Piezo1 loss of function or overactivation plays a crucial role in the pathogenesis of many common brain diseases." (PMID 37366640, 2023). "Investigating the pathophysiological mechanisms through which Piezo1‐mediated mechanotransduction affects brain function will give us a novel entry point for the diagnosis and treatment of numerous brain diseases." (PMID 37366640, 2023). "Below we summarize the roles of Piezo1 in mediating brain disease processes." (PMID 37366640, 2023). "Further studies are needed to determine whether Piezo1 acts in synergy with TRPV‐mediated mechanical signaling to promote brain disease." (PMID 37366640, 2023). "Notably, when using Piezo1 as a therapeutic strategy for brain disorders, the dual role of Piezo1, such as anti‐ versus pro‐inflammatory, needs to be considered." (PMID 37366640, 2023). "However, pharmacological studies on Piezo1 are currently limited, particularly in brain diseases." (PMID 37366640, 2023).
gastrointestinal tumors (2 papers, 2024 to 2025). "Other malignancies: Beyond digestive system tumors, Piezo1 also demonstrates high plasticity as a “mechanotransduction–signaling hub” in central nervous system, hematological, and prostate malignancies." (PMID 40821847, 2025).
musculoskeletal disorders (2 papers, 2023 to 2024). "Nevertheless, the Piezo1 channel is a promising target for the development of new types of drugs in musculoskeletal disorders." (PMID 37047487, 2023).
neurodevelopmental disorder (2 papers, 2023 to 2025). A behavioral and cognitive disorder with onset during the developmental period that involves impaired or aberrant development of intellectual, motor, or social functions. "Positions of the selected PIEZO1 CpG sites human genome assembly GRCh37 (hg19), percentage and range for DNAm level in each CpG sites in the two samples (NDs = neurodevelopmental disorders; TD = typical development)." (PMID 40823415, 2025).
adenocarcinoma (1 paper, 2025). A common cancer characterized by the presence of malignant glandular cells. "In COAD, adenocarcinoma patients showed heightened PIEZO1 expression." (PMID 40977743, 2025).
diseases of the central nervous system (1 paper, 2023). "However, the effect and mechanism of the activation or expression of PIEZO1 in diseases of the central nervous system (CNS) remain unclear." (PMID 36765838, 2023).
gastrointestinal disorders (1 paper, 2025). "This deeper understanding will not only provide crucial insights into the physiological function of Piezo1 but may also unveil potential therapeutic targets for gastrointestinal disorders associated with impaired SMC function or calcium signaling abnormalities." (PMID 40097724, 2025).
myopathy (1 paper, 2025). A disease of the muscle in which the muscle fibers do not function properly. "A comparison of five nonmyopathy human heart samples with 35 diverse human hypertrophic obstructive cardiomyopathy heart samples also suggested increased PIEZO1 mRNA in myopathy." (PMID 40721314, 2025). "Comparison of RNA sequencing data for 29 nonfailing and 31 ischemic cardiomyopathy hearts suggested increased PIEZO1 and PIEZO2 mRNA in myopathy." (PMID 40721314, 2025). "Upregulated PIEZO1 mRNA and PIEZO1 proteins were also suggested in a separate study of human dilated cardio-myopathy heart samples, with no change in PIEZO2 mRNA." (PMID 40721314, 2025).
skeletal muscle disorder (1 paper, 2022). A disease involving the skeletal muscle tissue. "All findings reported so far agree with the idea that Piezo1 channels represent a novel, powerful molecular target to develop new therapeutic strategies for preventing or ameliorating skeletal muscle disorders characterized by an impairment of tissue regenerative potential." (PMID 35743058, 2022).
PIEZO1 also shares sentences with these, for which no sentence is quoted: infectious disease (5 papers); cardiac arrhythmias (3); COVID-19 (3); knee osteoarthritis (3); aneurysm (2); Atrophy (2); bladder (2); Chylothorax (2); diabetic kidney disease (2); glycogen storage disease IV (2); Huntington's chorea (2); hypertrophy (2); lymphangiectasia (2); lymphatic malformation (2); mucopolysaccharidosis VII (2); open-angle glaucoma (2); peripheral nerve injury (2); rheumatoid arthritis (2); Spherocytosis (2); thyroid cancer (2); amyotrophic lateral sclerosis (1); Arterial thrombosis (1); atopic dermatitis (1); autosomal dominant disease (1); bile duct cancer (1); binge eating disorder (1); brain edema (1); bronchopulmonary dysplasia (1); cerebral small vessel disease (1); choanal atresia (1).
A further 88 diseases each share a sentence with PIEZO1 in 1 paper.